TFPI2 (tissue factor pathway inhibitor 2)
Diseases named in the same sentence as TFPI2 in open-access papers (continued):
Sharing a sentence is not in itself a finding about the gene and the disease.
adenoma (5 papers, 2021 to 2025). A neoplasm arising from the epithelium. "In stool samples, the methylation level of TFPI2 was higher in CRC than in adenoma (p < 0.001) and in adenoma than in the normal group (p < 0.001) (right)." (PMID 35004840, 2021). "SDC2/TFPI2-combined detection showed higher sensitivity not only to cancer samples but also to adenoma samples." (PMID 35004840, 2021). "SDC2/TFPI2-combined detection showed better diagnostic performance than SDC2 detection alone for CRC vs. normal and for adenoma vs. normal as well as for adenoma vs. CRC." (PMID 35004840, 2021). "The AUC value of SDC2/TFPI2 for CRC vs. adenoma was 0.72, with the specificity of 64.20% and sensitivity of 73.80%, which was lower than that of CRC vs. normal or adenoma vs. normal." (PMID 35004840, 2021). "When ML values were used as the detection index in ROC curve analysis, SDC2/TFPI2-combined detection also showed better diagnostic performance than SDC2 detection in discrimination between cancer and normal, between adenoma and normal, and between adenoma and cancer." (PMID 35004840, 2021). "However, the sensitivity of TFPI2 methylation in adenoma stool samples was only 21%." (PMID 33030559, 2021). "When the SDC2/TFPI2-combined PCR assay was performed in stool specimens, the AUC value of cancer vs. control was 0.98, with the specificity of 96.40% and sensitivity of 96.60%, and the AUC value of adenoma vs. control was 0.87, with the specificity of 95.70% and the sensitivity of 80.00%." (PMID 35004840, 2021). "The combined detection of TFPI2 and SDC2 showed both high specificity and sensitivity, especially for cancer and adenomas in the left colon for both tissue and stool specimens." (PMID 35004840, 2021). "For adenoma vs. normal, the AUC value of SDC2/TFPI2-combined detection was 0.87 (95% CI: 0.81–0.92) with the specificity of 95.70% and sensitivity of 80.00%, while the AUC value of SDC2 detection was 0.64 (95% CI: 0.57–0.71) with the specificity of 99.30% and sensitivity of 44.20%." (PMID 35004840, 2021). "Among stool samples, 55.3% CRC samples and 25.3% adenoma samples with an SDC2 Ct value larger than 38 (false-negative) showed positive results in TFPI2 MSP assays." (PMID 35004840, 2021). "One was the panel consisting of methylated BMP3/NDRG4/VIM/TFPI2/mutant KRAS, β-actin, and Hb-level (and later refined and commercialized as Cologuard®), which in stool detected CRC with 87% sensitivity, adenoma with 82% sensitivity, and demonstrated a specificity of 93%." (PMID 33030559, 2021). "In a study of plasma, the CRC sensitivity of TFPI2 methylation was only 7%, no adenomas were included, and the specificity was 98%." (PMID 33030559, 2021). "TFPI2 can improve the sensitivity of SDC2 methylation–specific detection of colorectal tumorous lesions while maintaining high specificity, in particular reducing the missed detection of left colon cancer and adenoma." (PMID 35004840, 2021). "Moreover, the TFPI-2 methylation level has been found to be high and frequent in the peritumoral mucosa of cancer patients and aberrant methylation of TFPI-2 has been identified in CRC development, during transition from its precursor-adenoma to cancer." (PMID 39153052, 2024). "In our study, the methylation level of CRC and adenoma was statistically different in stool samples; however, SDC2/TFPI2 did not differentiate CRC and adenoma well enough, which meant that the methylation pattern of adenoma was more similar to that of CRC." (PMID 35004840, 2021).
esophageal cancer (5 papers, 2010 to 2022). A primary or metastatic malignant neoplasm involving the esophagus. "Tissue factor pathway inhibitor 2 (TFPI2) encodes a member of the Kunitz-type serine proteinase inhibitor family, and was found to be down-regulated in 75% of esophageal carcinomas and in most esophageal carcinoma cell lines." (PMID 30233644, 2018). "Treatment with recombinant TFPI-2 protein inhibited tumor growth and metastasis of esophageal cancer." (PMID 21062455, 2010). "A similar gene TFPI2 was reported to be frequently methylated in esophageal cancer with a progression tendency, which indicated that TFPI methylation might also play roles in esophageal cancer." (PMID 28393072, 2017).
fibrosarcoma (5 papers, 2005 to 2025). A malignant mesenchymal fibroblastic neoplasm affecting the soft tissue and bone. "Previous studies have demonstrated that tissue factor pathway inhibitor-2 (TFPI-2) is associated with fibrosarcoma and that downregulation of TFPI-2 is associated with tumor growth/metastasis." (PMID 40801564, 2025). "There are reports of TFPI-2 mRNA absence in cancer cell lines of choriocarcinoma, fibrosarcoma, and pancreatic adenocarcinoma." (PMID 33947134, 2021). "This role of TFPI-2 in cancer invasion was recently supported by injecting fibrosarcoma cell lines expressing active or inactive forms of TFPI-2 in mice." (PMID 15685245, 2005). "PSAP’s interaction with TFPI-2 also presents a vulnerability in fibrosarcoma." (PMID 40801564, 2025). "On the other hand, as supported by findings obtained with a human fibrosarcoma cell line (HT-1080) and normal human fibroblasts, the RAS oncogene, which can be mutated in NSCLC, may also contribute to a downregulation of TFPI-2 gene expression." (PMID 15685245, 2005). "The findings indicate that TFPI-2 reduces the invasive and migratory capabilities of tumor cells by interacting with PSAP, offering a novel viewpoint and potential target for fibrosarcoma treatment." (PMID 40801564, 2025). "It has been reported that TFPI-2 diminishes plasmin- and trypsin-mediated activation of pro-MMP-1 and pro-MMP-3, leading to decreased ECM degradation and invasion of HT-1080 fibrosarcoma cells." (PMID 39153052, 2024). "Correspondingly, TFPI-2 mRNA has been shown to be absent in choriocarcinoma, fibrosarcoma, and pancreatic cancer cell lines." (PMID 33947134, 2021).
lymph node metastasis (5 papers, 2005 to 2021). "We found that multiple clinicopathologic features, such as tumor size, skin involvement, lymph node metastasis, histologic grade, clinical stage, and vessel invasion, were significantly correlated with the mean-density of TFPI-2 staining (P<0.05)." (PMID 23497249, 2013). "TFPI-2 expression was significantly correlated with tumor size, lymph node metastasis, histologic grade, clinical stage, and vessel invasion." (PMID 23497249, 2013). "Grading of expression of TFPI-2 was significantly associated with histopathological, FIGO stage, lymph node metastasis and HPV infection." (PMID 22208663, 2012). "Finally, we also found that TFPI-2 gene promoter was more frequently hypermethylated in patients with lymph node metastases." (PMID 15685245, 2005). "Decreased TFPI-2 gene expression and hypermethylation were more frequently associated with stages III or IV NSCLC (eight out of 10, P=0.02) and the TFPI-2 gene promoter was more frequently hypermethylated in patients with lymph node metastases (eight out of 16, P=0.02)." (PMID 15685245, 2005). "In contrast, the grading expression of TFPI-2 was significantly having a decreasing trend with FIGO stage, lymph node metastasis and HPV infection." (PMID 22208663, 2012).
metastatic disease (5 papers, 2014 to 2025). "Metastatic tumors also have higher TFPI2 promoter methylation than localized tumors." (PMID 40361374, 2025). "PTN, MK, PVRL4, EPHA2, TFPI-2, hK11, SYND1, ANGPT2 and hK14 were found elevated in the metastatic disease when compared to cancer-free, CPG1 and/or CPG5 groups." (PMID 33288843, 2021). "In addition, we successfully established a metastatic tumor model in animals by the intravenous injection of TFPI-2-expressing OC2 cells, and observed a marked inhibitory effect of TFPI-2 in the formation of lung tumor nodules, demonstrating that TFPI-2 is a silenced tumor suppressor gene in OSCC." (PMID 25179542, 2014).
preeclampsia (5 papers, 2014 to 2025). Preeclampsia is a hypertensive disorder of pregnancy that is characterized by new-onset hypertension with proteinuria presenting after 20 weeks of gestation, and depending on mild or severe forms may initially present with severe headache, visual disturbances, and hyperreflexia. "This review aims to provide a better understanding of TFPI1 and TFPI2 in the pathophysiology of preeclampsia and discuss the underlying mechanisms." (PMID 37238908, 2023). "Clinical studies have demonstrated marked alterations in TFPI2 expression in placental tissues and maternal circulation in cases of gestational hypertension." (PMID 40361374, 2025). "Conversely, maternal plasma TFPI2 levels are notably decreased in women with gestational hypertension relative to normotensive controls." (PMID 40361374, 2025). "This paradox indicates a complex regulatory dysregulation involving TFPI2 synthesis, release, or clearance in the context of gestational hypertension." (PMID 40361374, 2025). "Although TFPI2 overexpression in placental tissue is thought to enhance PPARγ levels, PPARγ expression is paradoxically diminished in gestational hypertension, contributing to an exacerbated inflammatory milieu." (PMID 40361374, 2025). "Low expression of GPC3 in placenta of preeclampsia results in an enhanced influx of TFPI2 into the maternal circulation." (PMID 37238908, 2023). "In this review, we summarize our current understanding of the biological functions of TFPI1 and TFPI2 and discuss future directions in preeclampsia research." (PMID 37238908, 2023). "The results showed a significantly increased TFPI2 mRNA level and decreased expression of miR-195 in preeclampsia patients compared to normal samples." (PMID 37559681, 2023). "TFPI2 was also found to be involved in the regulation of methylation status on the promoter region in preeclampsia placentas." (PMID 37559681, 2023). "In the current study, we discovered that TFPI2 mRNA levels were significantly upregulated in preeclampsia tissues and were negatively correlated with miR-195 expression levels." (PMID 37559681, 2023). "The aim of this review is to summarize recent data on the role of TFPI1 and TFPI2 in normal pregnancy and preeclampsia and discuss the impacts of TFPI protein family on the pathophysiology of preeclampsia." (PMID 37238908, 2023). "To explore the relationship between TFPI2 and miR-195, we compared the messenger ribonucleic acid (mRNA) expression levels of TFPI2 and miR-195 in the preeclampsia and normal pregnancy cohorts." (PMID 37559681, 2023). "In conclusion, this review summarizes recent advances in our knowledge of TFPI1 and TFPI2 in pathogenesis of preeclampsia." (PMID 37238908, 2023). "Maternal serum TFPI2 concentrations have been reported to be significantly increased in the preeclampsia group relative to the normal pregnant group." (PMID 37238908, 2023). "In our study, we found a negative correlation between TFPI2 and miR-195 expression in preeclampsia patients and showed TFPI2 to be a target gene of miR-195." (PMID 37559681, 2023). "On the other hand, TFPI2 expression has also been reported to be significantly lower in the preeclampsia group than in controls." (PMID 37238908, 2023). "Preeclampsia is associated with the increased t-PA, thrombomodulin, TAT, PAI-1, TF, TFPI1, and TFPI2 levels, decreased fibrinogen, antithrombin III, and PAI-2 levels, and increased fibrinolysis (e.g., D-dimer) compared to the normotensive controls." (PMID 37238908, 2023). "The messenger ribonucleic acid (mRNA) levels of miR-195 and tissue factor pathway inhibitor 2 (TFPI2) were measured in placental tissues derived from normal and preeclampsia patients by real-time polymerase chain reaction (PCR)." (PMID 37559681, 2023). "In particular, the altered expression of TFPI2 was reportedly identified in early forms of preeclampsia." (PMID 37238908, 2023).
preeclampsia (continued). "The expression of TFPI-2 has been reported to be significantly upregulated in both the serum and placenta of preeclampsia patients, and TFPI-2 has been demonstrated to play a crucial role in regulating trophoblast cells." (PMID 37559681, 2023). "TFPI2, as a suppressor gene, is known to be dysregulated in multiple human disorders, including preeclampsia and various cancers, where its expression is inversely related to an increasing grade of malignancy." (PMID 32784482, 2020). "Notably, a significant negative correlation (p = 0.0021) was observed between the mRNA level of TFPI2 and miR-195 in preeclampsia patients." (PMID 37559681, 2023). "miR-195 expression was negatively correlated with TFPI2 mRNA levels in preeclampsia patients." (PMID 37559681, 2023). "Therefore, it is of great interest to assess which marker best predict the risk for development of preeclampsia using the TFPI1- and TFPI2-specific immunoassays." (PMID 37238908, 2023). "TFPI1 and TFPI2 may function as new predictive biomarkers for preeclampsia and navigate precision therapy." (PMID 37238908, 2023). "Here, we summarize the biological activities of TFPI1 and TFPI2 in preeclampsia." (PMID 37238908, 2023). "Many studies have demonstrated that TFPI2 plays a role in the development of preeclampsia." (PMID 37559681, 2023). "Interestingly, experimental animal models have demonstrated that inhibition of the placental TFPI2 expression may lead to prevention of the development of preeclampsia." (PMID 37238908, 2023). "A better understanding of the biological functions of TFPI2 may help develop optimal therapeutic strategies not only for cancer and VTE, but also for preeclampsia." (PMID 37238908, 2023). "To date, however, no articles have compared total TFPI, free TFPI1, and free TFPI2 in plasma, platelets, and placental tissues of women with normal pregnancy and preeclampsia." (PMID 37238908, 2023).
Barrett esophagus (4 papers, 2018 to 2025). Esophageal lesion lined with columnar metaplastic epithelium which is flat or villiform. "The optimum biomarker to diagnose Barrett’s oesophagus was TFPI2 with a sensitivity and specificity of 82.2% and 95.7%, respectively." (PMID 29084829, 2018). "TFPI2, TWIST1, ZNF345 and ZNF569 methylation have promise as diagnostic biomarkers for Barrett’s oesophagus when used in combination with a simple and cost effective non-endoscopic cell collection device." (PMID 29084829, 2018). "In recent years, esophageal sponge cytology combined with biomarkers, like TFF3, tissue factor pathway inhibitor 2 (TFPI2), vav guanine nucleotide exchange factor 3 (VAV3), and microRNA, have been validated to have high efficiencies in detecting Barrett's esophagus and associated adenocarcinoma." (PMID 39856802, 2025). "Although the focus of this study was non-dysplastic Barrett’s oesophagus, it is interesting to note that Kaz et al33 have shown that TFPI2 methylation persists in high-grade dysplasia and adenocarcinoma." (PMID 29084829, 2018).
choriocarcinoma (4 papers, 2005 to 2021). An aggressive malignant tumor arising from trophoblastic cells. "A previous study indicated that TFPI-2 gene expression inhibits the growth of choriocarcinoma by inducing choriocarcinoma cell apoptosis." (PMID 24396436, 2014).
endometrial cancer (4 papers, 2005 to 2025). Primary or metastatic malignant neoplasm involving the endometrium (mucous membrane that lines the endometrial cavity). "In a study of 207 endometrial cancer cases, TFPI2 ≥ 177 pg/mL was associated with advanced age, diabetes, disease stage, and metastasis, with higher levels predicting poorer OS." (PMID 40361374, 2025). "Initially characterized as a tumor suppressor gene, TFPI2 exhibits elevated serum levels in patients with ovarian and endometrial cancers compared to healthy individuals, correlating with poor prognostic outcomes." (PMID 40361374, 2025). "Moreover, a series of studies have demonstrated that increased circulating TFPI2 levels correlate with adverse prognosis in ovarian and endometrial cancers." (PMID 40361374, 2025). "In endometrial cancer, all 13 cases of endometrial clear cell carcinoma showed TFPI2 positivity, while only 11 of 42 non-endometrial clear cell carcinoma cases did, indicating TFPI2 specificity for endometrial clear cell carcinoma." (PMID 40361374, 2025). "Furthermore, as seen in the training set, TFPI2 levels >345 pg/mL were also observed in a subset of patients with serous-type EOC (5 of 17) or endometrioid-type endometrial cancer (2 of 26)." (PMID 27798689, 2016). "Notably, in ovarian and endometrial cancers, interactions with M2-polarized macrophages may upregulate TFPI2 expression, thereby enhancing metastatic potential." (PMID 40361374, 2025). "A study of 328 endometrial cancer patients found that TFPI2 levels increased with disease stage and were linked to poorer five-year survival rates, although no direct correlation with immunohistochemical TFPI2 expression was found." (PMID 40361374, 2025). "TFPI-2 protein synthesis has also recently been studied by immunohistochemical procedures in other different tumours (laryngeal, breast, gastric, colon, pancreatic, renal and endometrial cancer) and was shown to decrease when the degree of malignancy increased." (PMID 15685245, 2005). "However, in a study of 105 type II endometrial cancer cases, TFPI2 was detected in 39 cases (37%), with no significant variation across histological subtypes." (PMID 40361374, 2025).
Hyperglycemia (4 papers, 2018 to 2025). An increased concentration of glucose in the blood. "Poly (ADP-ribose) polymerase 1 (PARP1) represses TFPI2 in VSMCs under hyperglycemia by promoting DNA methylation." (PMID 40361374, 2025). "Overexpression of TFPI2 enhances plaque stability, induces reparative M2 macrophage polarization, and mitigates hyperglycemia-induced vascular damage." (PMID 40361374, 2025). "Further experiments revealed that hyperglycemia-induced PARP1 promotes diabetic neointimal hyperplasia via down-regulating TFPI-2 (which normally suppresses proliferation of vascular smooth muscle cells)." (PMID 39153052, 2024). "In cardiovascular diseases, previous studies have indicated that TFPI2 can inhibit hyperglycaemia-induced vascular smooth muscle cell (VSMC) migration and neointimal hyperplasia by inhibiting the expression and activity of MMPs." (PMID 37915070, 2023). "We previously reported that tissue factor pathway inhibitor-2 (TFPI2) was downregulated in response to hyperglycaemia at least partially via DNA hypermethylation of its promoter." (PMID 37915070, 2023). "Western blot analysis also confirmed that TFPI2 overexpression inhibited hyperglycaemia-induced M1 macrophage polarization and promoted transition to reparative M2 macrophages." (PMID 37915070, 2023). "We previously reported that tissue factor pathway inhibitor-2 (TFPI2) was downregulated in response to hyperglycaemia and that it played a pivotal role in extracellular matrix (ECM) degradation and cell migration." (PMID 37915070, 2023). "Interestingly, the researchers concluded that hyperglycemia silences TFPI-2 via PARP1-mediated TFPI-2 promoter methylation." (PMID 39153052, 2024). "In our previous study, we discovered that TFPI2 was downregulated in hyperglycaemia-stimulated VSMCs, in which PARP1 activation plays a key role in promoting DNA methylation of the TFPI2 promoter and TFPI2 downregulation." (PMID 37915070, 2023). "Our microarray experiments demonstrated that metformin upregulated downstream targets in VEGFA pathway; MMP16, FABP4, ROCK1, TFPI2, CXCL-8, and LY96 under hyperglycemia-CoCl2, which play a part in cell migration." (PMID 29351188, 2018). "Similarly, hyperglycemia-induced endothelial-mesenchymal transition was limited in the absence of TFPI-2." (PMID 39153052, 2024).